GSDMD (gasdermin D)
Diseases named in the same sentence as GSDMD in open-access papers (continued):
Sharing a sentence is not in itself a finding about the gene and the disease.
glioma (continued). "Additionally, GSDMD was upregulated in Lower Grade Glioma (LGG) and Melanoma (SKCM), while showing downregulation in Uterine Carcinosarcoma (UCS)." (PMID 40491921, 2025). "Inflammation often accompanies immune responses, and to further explore the association between pyroptosis and immune cell infiltration, GSVA analysis showed that with the increase of GSDMD, glioma tissues often had more immune cell infiltration and inflammatory responses." (PMID 39069522, 2024). "The CCK-8 results showed that GSDMD knockdown inhibited the proliferation of glioma cells." (PMID 37371484, 2023). "Furthermore, the in vitro and in vivo experiments revealed that GSDMD knockdown inhibited glioma proliferation, migration, and growth in vivo." (PMID 37371484, 2023). "GSDMD expression and age are independent prognostic factors for glioma patients (p < 0.0001)." (PMID 37371484, 2023). "Importantly, the expression pattern of GSDMD showed differences according to the status of IDH1/2 mutation and 1p19q co-deletion, indicating detailed molecular characteristics of gliomas and the biological link of the inflammasome." (PMID 37723542, 2023). "Furthermore, we conducted experiments with nude mice bearing NC and si-GSDMD U87 glioma cells, and further studies showed GSDMD knockdown suppressed tumor growth in vivo." (PMID 37371484, 2023). "GSDMD knock-down inhibited the progression of glioma both in vitro and in vivo." (PMID 37371484, 2023). "As an effector of pyroptosis, GSDMD is involved in the progression of glioma." (PMID 38002346, 2023). "Furthermore, we performed in vivo and in vitro experiments that revealed knocking down GSDMD is a novel target in glioma treatment." (PMID 37371484, 2023). "GSDMD, as an effector of pyroptosis, has the potential to be a biomarker for prognosis in glioma." (PMID 38002346, 2023). "To further investigate the relationship between GSDMD expression and clinical characteristics, we divided the cancer cases into GSDMD high- and low-expression according to the median expression of GSDMD and assessed the correlation of GSDMD expression with the OS of glioma patients." (PMID 37371484, 2023). "In addition, CCK-8, colony formation, and transwell assays were performed to investigate the impact of GSDMD on glioma cells." (PMID 37371484, 2023). "GSDMD is a promising prognostic biomarker and a potential target for glioma treatment." (PMID 37371484, 2023). "In addition, the transwell assays revealed that knocking down GSDMD inhibited the migration of glioma cells." (PMID 37371484, 2023). "Therefore, GSDMD is a promising prognostic biomarker and a novel therapeutic target for patients with glioma." (PMID 37371484, 2023). "Then, we also compared GSDMD at a protein level in normal glial cells and glioma cells using IHC." (PMID 37371484, 2023). "Therefore, we summarized that GSDMD can promote glioma progression by increasing the ratio of CAFs and macrophages to induce an immunosuppressive TME." (PMID 37371484, 2023). "Therefore, the single-cell analysis indicated that GSDMD promotes glioma progression by regulating CAFs and macrophages." (PMID 37371484, 2023). "Abundant TAM (CD68+/CD163+) infiltration was observed in glioma tissues with high GSDMD expression." (PMID 35990696, 2022). "Low expression of GSDMD was related to longer overall survival in glioma." (PMID 35896522, 2022). "Taken together, these findings gave us a hint that glioma cells with high GSDMD expression might present with increasing sensitivity to chemotherapeutic drugs and decreasing drug resistance." (PMID 34830775, 2021). "Then we investigated the prognostic role of GSDMD in predicting TMZ response in glioma patients." (PMID 34830775, 2021). "We tried to found association between GSDMD expression and TMZ response in glioma." (PMID 34830775, 2021). "Moreover, GSDMD expression was obviously elevated in TMZ-treated glioma cells and became more noticeable as the drug concentration increased." (PMID 34830775, 2021).
glioma (continued). "In addition, we explored the modulatory mechanisms of GSDMD in glioma progression." (PMID 37371484, 2023). "Therefore, GSDMD also plays a role in regulating the cell states of glioma." (PMID 37371484, 2023). "Moreover, the glioma patients with high expression of GSDMD had shorter OS." (PMID 37371484, 2023). "Furthermore, GSEA analysis confirmed the immunomodulatory effects of GSDMD on glioma progression." (PMID 37371484, 2023). "Thus, we speculated that GSDMD regulated glioma progression by influencing the tumor immune microenvironment." (PMID 37371484, 2023). "Furthermore, gasdermin D may be a principal potential biomarker and play key roles in pyroptosis-inducible therapy combined with immunotherapy in glioma." (PMID 35784306, 2022). "Pyroptosis offers novel therapeutic strategies, such as targeting GSDMD, NLRP3, or ncRNAs like miR-214 and circWEE1, to enhance TMZ sensitivity, overcome resistance, and curb glioma progression." (PMID 41291696, 2025). "In glioma cells treated with temozolomide (TMZ), the expression of pyroptosis markers, including GSDMD, caspase-1, and IL-1β, significantly increases, accompanied by morphological changes indicative of pyroptosis." (PMID 39949740, 2025). "Pyroptosis induced by GSDMD and NLRC4 in high-grade gliomas can promote the progression of gliomas and enhance the sensitivity of these tumors to immune checkpoint therapy by recruiting immune cells." (PMID 38304430, 2024). "GSDMD shows promise as a novel biomarker for prognosis in cancer, including CRC and brain lower-grade glioma." (PMID 38002346, 2023). "Therefore, GSDMD knockdown could inhibit glioma progression both in vitro and in vivo." (PMID 37371484, 2023). "However, the precise effect of GSDMD on glioma progression remains unknown." (PMID 37371484, 2023). "The analysis of the data of glioma samples from TCGA-693 showed that GSDMA and GSDMD were more highly expressed in grade IV than in grade II–III samples." (PMID 35784306, 2022). "The differential gene analysis in the current study showed that CASP4 expression is associated with several other important molecules of pyroptosis, including GSDMD, CASP1, IL-18, and TLR2, in gliomas." (PMID 36713560, 2022). "A previous study showed that GSDMD expression was negatively correlated with OS and increased after TMZ treatment in a time-dependent manner in glioma, which is consistent with our results." (PMID 35784306, 2022). "We conculded that GSDMD was a novel prognostic biomarker, as well as TMZ-treatment response marker in glioma." (PMID 34830775, 2021). "High GSDMD expression correlated with greater infiltration of neutrophil/macrophage in LGG and GBM, which revealed the important role of GSDMD in remodeling glioma microenvironment and promoting tumor progression." (PMID 34830775, 2021). "In order to illustrate expression pattern and prognostic role of GSDMD and GSDME in glioma, we conducted further experimental validations." (PMID 34830775, 2021). "In regard to glioma, several small molecules and drugs, such as galangin (through caspase-3/GSDME axis), benzimidazole (through NF-kB/NLRP3/GSDMD axis), kaempferol (through GSDME and ROS), and AT7519 (through caspase-3 cleavage of GSDME) have shown the capability of inducing pyroptosis." (PMID 41291696, 2025). "Cox regression, Kaplan–Meier analysis, and IHC results showed that GSDMD might be a novel biomarker for the prognosis and TMZ sensitivity in glioma." (PMID 37723542, 2023). "GSDMD was more highly expressed in glioma tissues compared to normal tissues, and a higher level of GSDMD indicated a shorter OS in patients with glioma." (PMID 37371484, 2023). "While in the CGGA dataset, we found that age (>60 years), WHO grade IV, IDH 1/2 wild-type, high GSDMD and GSDME expression could be used independently to predict the prognosis of gliomas patients." (PMID 34830775, 2021). "GSDMD was a novel prognostic biomarker, as well as TMZ-treatment response marker in glioma." (PMID 34830775, 2021).
glioma (continued). "Only GSDMD expression was upregulated in glioma compared with nontumor brain tissues both in the public datasets and in-house cohort." (PMID 34830775, 2021). "IDH-mut with or without 1p19q co-deletion glioma patients had lower GSDMD expression that those with IDH1-wt, which indicated strong association between GSDMD and molecular features and therefore with its malignancy." (PMID 34830775, 2021). "Then positive correlations were shown between GSDMD and CD163 expression in glioma tissues by IHC." (PMID 34830775, 2021). "Results presented above indicated GSDMD and GSMDE might play crucial roles in the malignancy process of glioma, and be potential biomarkers in predicting prognosis of GBM." (PMID 34830775, 2021). "We found that only GSDMD expression was upregulated in glioma compared with nontumor brain tissues both in the public datasets and in-house cohort." (PMID 34830775, 2021). "During the treatment of glioma, TMZ could be selected according to the expression levels of GSDMD, which was obviously upregulated in GBM, thereby increasing the sensitivity to chemotherapeutic drugs and reducing drug resistance." (PMID 34830775, 2021). "GSDMD could be used as an independent prognostic biomarker, as well as TMZ-treatment response marker in glioma." (PMID 34830775, 2021). "GSDMD was overexpression in glioma compared to nontumor tissues." (PMID 35896522, 2022). "Inflammasome/GSDMD/IL-1β axis has not been investigated in glioma." (PMID 34830775, 2021). "However, GSDMD is upregulated in glioma compared with that in non-tumour brain tissues." (PMID 39616223, 2024). "However, the roles of GSDMD in glioma genesis and progression have not been elucidated." (PMID 37371484, 2023). "Considering the expression of GSDMD—the primary executor of pyroptosis—the glioma pyroptosis subtype C1 and a high GPI may represent a potentially activated status of pyroptosis, while the glioma pyroptosis subtype C2 and C3 and a low GPI may represent a potentially suppressed status of pyroptosis." (PMID 35784306, 2022). "However, whether GSDMD has important functions in mediating the IDH-induced EMT process in glioma is not well established." (PMID 34830775, 2021). "Results of Western blot analysis revealed that GSDMD, not GSDME was elevated in glioma tissues when compared with non-brain tumor tissues." (PMID 34830775, 2021).
ischemic stroke (24 papers, 2019 to 2025). A stroke disorder caused by obstruction of blood flow to the brain, due to thrombotic (local blood clot formation) or embolic (due to a blood clot or other material traveling from another site) event. "This study underscores the significant therapeutic potential of the herbal mixture Astragalus mongholicus (AM) and Scutellaria baicalensis (SB) in mitigating inflammation and pyroptosis via modulation of the NLRP3/Caspase-1/GSDMD pathway in ischemic stroke." (PMID 39859214, 2025). "The NF-κB/NLRP3/GSDMD pathway is a significant anti-pyroptotic and neuroprotective pathway after ischemic stroke." (PMID 40717974, 2025). "In ischemic stroke, GSDMD ablation results in infarct size reduction, inflammation, and improved survival." (PMID 40331993, 2025). "Cerebral ischemia-reperfusion damage was alleviated to different degrees, suggesting that the NF-κB/NLRP3/Caspase-1/GSDMD signaling pathway is involved in the pathogenesis and healing of ischemic stroke." (PMID 39199474, 2024). "GSDMD-mediated pyroptosis has been related to several diseases and pathological states, including acute kidney injury, ischemic stroke, and cancer (see Section 5)." (PMID 37627547, 2023). "It’s also reported that GSDMD-KO mice showed lower modified NSS scores than WT mice in an ischemic stroke animal model." (PMID 35669106, 2022). "In ischemic stroke, multiple inflammasomes (NLRC4, NLRP1, NLRP3, NLRP6, AIM2) have been implicated, with AIM2 uniquely recognizing cytosolic dsDNA to drive AIM2-ASC-caspase-1 complex formation and GSDMD-mediated pyroptosis." (PMID 41344159, 2025). "Furthermore, edaravone dexborneol exerted neuroprotective effect by inhibiting NF-κB/NLRP3/GSDMD signaling pathway and inflammatory factors (IL-1β and IL-18) in experimental ischemic stroke." (PMID 38902691, 2024). "More specifically, ischemic stroke results in the translocation of p50 and p65 into the nucleus of microglia, leading to the activation of NF-κB and consequently triggering the transcription of target genes such as gasdermin D (GSDMD), NLRP3, IL-1β, and IL-18." (PMID 36677800, 2023). "Momentously, we also noted that activated microglia are the primary subset of cells with GSDMD immunoreactivity that are responsible for pyroptosis, similar to other neuroinflammation-relational disorders including ischemic stroke, post-cardiac arrest brain injury, and spinal cord injury." (PMID 35689216, 2022). "Similarly, inhibiting AIM2 inflammasome activation or double-stranded DNA (a trigger of the AIM2 inflammasome) alleviates GSDMD-induced pyroptosis and ameliorates brain injury after ischemic stroke." (PMID 34740380, 2021). "In summary, blocking GSDMD expression might serve as a potential therapeutic strategy for ischemic stroke." (PMID 33329317, 2020). "It has also been claimed that targeting GSDMD could be a strategy for ischemic stroke therapy." (PMID 37627547, 2023). "This study showed that NBP, which was approved for ischaemic stroke by the State Food and Drug Administration in China in 2002, provides protection against pressure overload-mediated deleterious myocardial hypertrophy by directly binding to GSDMD-N protein and reducing GSDMD-mediated inflammation." (PMID 34168567, 2021). "Therefore, a miRNA modulator and/or genetic regulator targeting GSDMD might serve as a promising alternative molecular drug for the treatment of ischemic stroke." (PMID 33329317, 2020). "This study planned to mainly evaluate the effects of AS-IV and HSYA on NLRP3 inflammasomes after ischemic stroke and further elucidate the anti-pyroptotic effects via the NLRP3/Caspase-1/GSDMD pathway." (PMID 39199474, 2024). "It is demonstrated that not only GSDMD but also NLRC4 and NLRP3 have been identified to promote microglia or neuronal pyroptotic cell death in ischemic stroke." (PMID 35774778, 2022). "Accordingly, ischemic stroke was found to significantly increase the levels of cleaved caspase-1, ASC, NLRP3, cleaved GSDMD, IL-1β, and IL-18." (PMID 33584203, 2020).
ischemic stroke (continued). "Gasdermin D (GSDMD) is a newly discovered key molecule of cell pyroptosis, but its biological function and precise role in ischemic stroke are still unclear." (PMID 33329317, 2020). "Although it has been proven that GSDMD plays a crucial role in the ischemic stroke and experimental autoimmune encephalomyelitis mouse models, the role of GSDMD in neuroinflammation progression after TBI has not been investigated." (PMID 35669106, 2022). "It has also been shown that knockdown of Gasdermin-D (GSDMD) or inhibition of GSDMD with GSDMD-C, afenide, etc. can effectively reduce the secretion of mature IL-1β and IL-18 and microglia pyroptosis and subsequent ischemic stroke-related brain injury." (PMID 35860297, 2022). "A study treating ischemic stroke with a monoclonal antibody targeting TNF- α found that the antibody favorably modulates microglial M1 / M2 polarization, rebalances Th 17 / Treg, cell dynamics, and suppresses Caspase-8-mediated GSDMD cleavage to prevent microglial pyroptosis." (PMID 40786625, 2025). "No GSDMD-targeted inhibitors for the treatment of ischemic stroke are used the clinic." (PMID 36755018, 2023).
Cerebral ischemia (22 papers, 2020 to 2026). Restriction of arterial blood supply to the brain associated with insufficient oxygenation to support the metabolic requirements of the tissue. "J observed a time-dependent increase in the expression of pyroptosis-associated proteins in a cerebral ischemia model and found that GSDMD was mainly co-labeled in NeuN-positive cells (neurons)." (PMID 35153737, 2021). "Excessive activation of GSDMD at the infarct edge will aggravate post-ischemic brain injury, and the loss of GSDMD protein in the core area of infarction after cerebral ischemia may also lead to adverse outcomes of CIRI." (PMID 39139639, 2024). "This study confirmed that quercetin can directly bind to the NLRP3 protein and alleviate cerebral ischemia-induced inflammatory injury by inhibiting the activation of the NLRP3/Caspase-1/GSDMD pyroptosis axis and the release of downstream inflammatory factors." (PMID 41892344, 2026). "Western blot analysis demonstrated cerebral ischemia increased the levels of GSDMD-N (the activated form of GSDMD), and the increase of GSDMD-N was notably boosted by ChemR23 deletion in MCAO mice." (PMID 38178174, 2024). "The NF-κB/NLRP3/Caspase-1/GSDMD pathway is involved in cerebral ischemia-reperfusion injury, and its related molecules have become experimental targets for alleviating cerebral ischemia-reperfusion injury." (PMID 39199474, 2024). "The major components of XBJ, paeoniflorin and hydroxysafflor yellow A are identified can down-regulate GSDMD expression in depression and cerebral ischemia reperfusion models, respectively." (PMID 36467039, 2022). "The major components of XBJ, paeoniflorin and hydroxysafflor yellow A are identified can down-regulate GSDMD expression in depression mice and cerebral ischemia reperfusion models, respectively." (PMID 36467039, 2022). "GSDMD serves as a key executioner of pyroptosis in experimental cerebral ischemia and reperfusion model both in vivo and in vitro." (PMID 34901142, 2021). "NLRP3 inflammasome, involved in the regulation of inflammatory cascade, can simultaneously lead to GSDMD-executed pyroptosis in cerebral ischemia." (PMID 33153475, 2020). "Our study showed that full‐length GSDMD, as well as its p30 and p20 cleavage products, have upregulated expression in the acute phase of cerebral ischemia." (PMID 32343048, 2020). "Analogously, our study observed an upregulated expression of full-length GSDMD and its N-terminus cleavage product via NF-κB signal-primed inflammasome cascades in the acute phase of cerebral ischemia." (PMID 33153475, 2020). "In a rat stroke model, the protein GSDMD promptly increased and then climbed to a peak 24–48 h post-ischemia, indicating that pyroptosis occurs efficiently during cerebral ischemia injury." (PMID 33013286, 2020). "Furthermore, its major active components have been found to downregulate GSDMD expression, a key regulator of pyroptosis, in models of depression and cerebral ischemia–reperfusion." (PMID 40083378, 2025). "The mechanism may be downregulation of NFΚB/NLRP3/Caspase-1/GSDMD pathway protein expression and regulation of NLRP3 inflammasome-mediated pyroptosis associated with cerebral ischemia-reperfusion." (PMID 39199474, 2024). "This combination may alleviate cerebral ischemia-reperfusion injury in rats by downregulating the signaling molecules of the NF-κB/NLRP3/Caspase-1/GSDMD pathway." (PMID 39199474, 2024). "Additionally, GSDMD, as an important factor of pyroptotic death execution downstream of Caspase-1 (canonical inflammasome), directly participates in brain ischemia-reperfusion injury." (PMID 39199474, 2024). "Previous studies have also demonstrated that caspase-1 activation and subsequent GSDMD cleavage play key roles in pyroptosis and neuroinflammation in CNS diseases, such as cerebral ischemia and AD, and that the inhibition of caspase-1 activation can attenuate brain injury." (PMID 37921870, 2023).